VDR (vitamin D receptor)
Diseases named in the same sentence as VDR in open-access papers (continued):
Sharing a sentence is not in itself a finding about the gene and the disease.
Infertility (17 papers, 2015 to 2025). "On sequence analysis, a mutation rs 4588 SNP (Thr 436 Lys) was found in exon 11 of the VDBP gene of infertile females, and a C/T mutation was found at position 4,7846,396 in exon 9 of the VDR gene of infertile females." (PMID 38586664, 2024). "VDR polymorphisms are associated with infertility and a decrease in folliculogenesis, oocyte yield, fertilization, and pregnancy rates after controlled ovarian stimulation (COS) responses in assisted reproductive techniques (ART)." (PMID 38586664, 2024). "In the genetic models, statistical power was adequate for genotype and allele frequencies of reported gene polymorphisms, as well as relationships between individual VDR polymorphisms and the probability of infertility/RPL." (PMID 38816754, 2024). "Our results are supported by a study, which indicated VDR gene polymorphisms as a contributing factor for infertility in patients with UI." (PMID 38586664, 2024). "Regarding the evaluation of the connection between VDR gene polymorphisms and infertility/recurrent miscarriage in numerous single studies in different populations, the findings are contradictory." (PMID 38816754, 2024). "A subgroup analysis was also undertaken to investigate the possible significance of patient ethnicity or infertility etiology on the association between VDR polymorphisms and the risk of infertility." (PMID 38816754, 2024). "We meta-analyzed the VDR gene TaqI, BsmI, FokI, ApaI polymorphisms, and women/men infertility for the first time." (PMID 38816754, 2024). "The present study included a total of 22 articles and showed that the VDR gene TaqI polymorphism was associated with infertility susceptibility in women." (PMID 38816754, 2024). "The probable role of VD in the impairment of reproductive physiology and the relationship of VD deficiency (VDD), with VDR polymorphism and infertility in female subjects, has been explored." (PMID 38586664, 2024). "This meta-analysis suggests that vitamin D receptor gene variations may play a role in infertility risk and outcome." (PMID 38816754, 2024). "VDR gene polymorphism could contribute to the pathophysiology of infertility by influencing gene expression and mRNA stability, and hence the cellular and molecular processes associated with infertility etiology." (PMID 38816754, 2024). "Furthermore, expression studies are essential for fully comprehending the function of VDR polymorphisms in the etiology of infertility/recurrent miscarriage." (PMID 38816754, 2024). "In our study, subgroup analysis suggested that the VDR gene BsmI polymorphism was significantly associated with susceptibility to infertility for the comparison of (AA vs. aa), (AA vs. Aa), and recessive model, and was protective SNP in the over-dominant genetic model in Asian population." (PMID 38816754, 2024). "Furthermore, VDR ApaI (rs7975232) was found to be associated with infertility susceptibility in the PCOS subgroup, however, a protection association with idiopathic infertility was found." (PMID 38816754, 2024). "The identification of VDR polymorphisms specifically related to infertility and response to ovarian stimulation may help in a better understanding of processes for UI and affected ovarian reserves." (PMID 38586664, 2024). "Finally, our findings imply that VDR FokI and ApaI polymorphisms may be linked to infertility/recurrent miscarriage." (PMID 38816754, 2024). "Understanding the associations between VDR gene polymorphisms and the risk of developing PCOS and infertility is critical for improving the diagnosis, treatment, and management of this condition." (PMID 39866289, 2025). "There is a correlation between VDR gene polymorphisms and the risk of PCOS and infertility, according to the data that has been criticized." (PMID 39866289, 2025).
Infertility (continued). "It is essential to get an understanding of the relationships between VDR gene polymorphisms and the risk of developing PCOS and infertility in order to improve the diagnosis, treatment, and management of this disorder." (PMID 39866289, 2025). "VDR gene polymorphisms were shown to be significantly related to an elevated risk of PCOS and infertility in females, according to the findings of our study." (PMID 39866289, 2025). "The mean VDR values of infertile females (27.32 ± 7.45) were also significantly lower than fertile females (41.25 ± 8.1; p<0.001)." (PMID 38586664, 2024). "An ongoing argument on global VDD and the presence of VDR in reproductive tissues with an increased prevalence of infertility has encouraged us to conduct the study." (PMID 38586664, 2024). "The VDR gene is a potential gene for infertility because it controls several genes that participate in diverse molecular and cellular processes." (PMID 38816754, 2024). "With this context, the identification of VDR, NCOR1, and SMAD3 in this study must be evaluated further to explore their role in therapies for VD-deficient females with infertility." (PMID 38586664, 2024). "We wanted to identify the single nucleotide polymorphism (SNP) of VD binding protein (VDBP), the dysregulated pathways, and gene enrichment centered on interaction network analysis of VDR-VDBP in unexplained infertile females with VDD." (PMID 38586664, 2024). "Here, in this study, we observed for the first time that the sperm of men with unexplained infertility expressed the VDR gene." (PMID 36741485, 2023). "Due to the role of vitamin D in the immune system and fertility, this research aimed to evaluate the VDR gene expression in sperm samples obtained from unexplained infertile men and compare it with fertile cases." (PMID 36741485, 2023). "VDR was shown to be expressed in neck and post-acrosomal regions of spermatozoa, and found to be higher in normal men than in infertile men." (PMID 32503520, 2020). "As a result, VDR is also expressed on the male and female reproductive systems, studies suggest the role of vitamin D in infertility, with a lifetime prevalence of about 25%." (PMID 32259002, 2020). "An updated meta-analysis that incorporated more population studies might address research gaps in VDR gene polymorphisms as well as the risk for PCOS and infertility." (PMID 39866289, 2025). "According to our findings, VDR ApaI and FokI can have a role in infertility/recurrent miscarriage." (PMID 38816754, 2024). "Additionally, VDR knockout mice were infertile and had decreased folliculogenesis and CYP19A1 expression, whereas after supplementing with E2, the uterine weight increased." (PMID 37232725, 2023). "As well as for ESR1 and ESR2, VDR/KO mice (from in vivo studies) are infertile." (PMID 35353297, 2022). "Also it has been reported that in mice with knocked out vitamin D receptor (VDR) gene, impaired follicle development, gonadal malfunctions, decreased aromatase expression and activity, pregnancy complications, uterine hypoplasia and infertility can be seen." (PMID 26330851, 2015). "Medical treatments aimed at correcting expression defects of PTX3, VDR and other cumulus genes may emerge as a new approach to the treatment of PCOS-related infertility." (PMID 38167474, 2024). "The sperm of unexplained infertile men express VDR gene mRNA, although there was no vitamin D in seminal samples." (PMID 36741485, 2023). "The red cluster was dominated by female, infertility, semen quality, PCOS, and VDR." (PMID 36159484, 2022). "Although VDR polymorphismhas been reported as not being related to infertility in anendometriosis study, there is a need for further researchto clarify this particular issue." (PMID 29707935, 2018). "However, the decrease in mRNA expression of the VDR gene in unexplained infertile patients was not significantly lower than the fertile group." (PMID 36741485, 2023).
Infertility (continued). "Hence, vitamin D and VDR signaling might not be effective in the etiopathogenesis of unexplained infertility in men." (PMID 36741485, 2023).
liver steatosis (17 papers, 2016 to 2025). "In this context, VDR knockout mice exhibited exacerbated liver steatosis induced by HFD or methionine- and choline-deficiency." (PMID 38732118, 2024). "The presence of the VDR polymorphism rs2228570 was shown to be related to low serum vitamin D levels and to influence the development of fatty liver disease in recipients after living donor transplantation." (PMID 37175993, 2023). "Therefore, it was suggested that induction of hepatic VDR expression contributes to fat-associated hepatic steatosis by promoting hepatic lipogenesis and inhibiting lipid oxidation pathways." (PMID 37175993, 2023). "Elevated hepatic VDR levels have been associated with liver steatosis and, therefore, our results may have clinical relevance in epileptic pediatric patients on VPA therapy." (PMID 35807853, 2022). "Moreover, treatment with calcitriol increases VDR expression in peripheral cells, ameliorates systemic and tissue-associated inflammatory profile, reducing AT inflammation and liver steatosis in animal models." (PMID 33126575, 2020). "As elevated hepatic VDR levels have been associated with liver steatosis our results may have clinical relevance regarding hepatic steatosis in patients on VPA therapy, which is not uncommon as 60.9% of VPA-treated patients revealed potential steatosis by ultrasonography." (PMID 35807853, 2022). "Contradictory results were presented by an investigation demonstrating that VDR deletion protected against liver steatosis, dyslipidemia, and insulin resistance in apolipoprotein E (apoE) knockout (−/−) HFD mice." (PMID 38732118, 2024). "VDR activity has protective and detrimental effects on hepatic steatosis, a characteristic feature of NAFLD." (PMID 37175993, 2023). "Activation of VDR by calcipotriol improved insulin sensitivity and reduced hepatic steatosis in mouse liver macrophages." (PMID 37175993, 2023). "In contrast, a recent study showed that vitamin D supplementation had a protective effect on HFD-induced NAFLD through VDR induction and that VDR knockout mice showed worsening of HFD- or methionine- and choline-deficiency-induced liver steatosis." (PMID 35955597, 2022). "At age of 4–6 months, VDR KO mice developed spontaneous hepatic steatosis, while body mass was progressively decreased." (PMID 27895587, 2016). "Beyond its intestinal effects, VD supplementation reduced hepatic steatosis, pointing to a potential protective mechanism via hepatic VDR activation, which may alleviate NASH." (PMID 39765737, 2024). "Moreover, the mRNA levels of ANGPTL8 were found to correlate with both VDR mRNA and the extent of liver steatosis." (PMID 38732118, 2024). "The role of VDR in the development of hepatic steatosis was reported in vivo." (PMID 37175993, 2023). "Similarly, gut-specific VDR enhanced weight gain, adipose tissue inflammation, and the development of hepatic steatosis induced by HFD." (PMID 35807853, 2022). "On the other, VPA-mediated VDR activation may lead to detrimental effects since we demonstrated that VDR mediates experimental diet-induced liver steatosis." (PMID 35807853, 2022). "Furthermore, in a recent investigation, vitamin D improved hepatic insulin resistance and ameliorated liver steatosis in rodent models via the VDR-mediated activation of the hepatocyte nuclear factor 4α (HNF4α)." (PMID 33126575, 2020). "“Non-alcoholic fatty liver disease” (NAFLD), “non-alcoholic steatohepatitis” (NASH), “fatty liver”, “hepatic steatosis”, “metabolic-associated fatty liver disease” (MAFLD) were paired with “vitamin D”, “cholecalciferol”, “calcitriol”, “ and vitamin D receptor” (VDR) as search terms." (PMID 33126575, 2020). "In addition to this, FGF19 (the human ortholog of FGF15) has been suggested to improve adiposity and liver steatosis in obese mouse models and the mouse Fgf15 gene has been defined as a direct transcriptional target of VDR." (PMID 30609782, 2019).
liver steatosis (continued). "The potential involvement of the vitamin D/VDR axis in the pathogenesis and progression of MAFLD has been suggested by experimental studies linking vitamin D-mediated pathways to key processes leading to liver steatosis, inflammation, and fibrosis." (PMID 33126575, 2020).
myocardial infarction (17 papers, 2012 to 2024). Gross necrosis of the myocardium, as a result of interruption of the blood supply to the area, as in coronary thrombosis. "Our findings are consistent with those of a previous study, which found that the T/T genotype of the Bsm I (rs1544410) VDR polymorphism is more common among myocardial infarction CAD patients." (PMID 37259407, 2023). "The presented results suggest a potential association of the BsmI (rs1544410) and Taq1 (rs731236) VDR polymorphisms with CAD patients after myocardial infarction." (PMID 33863283, 2021). "In brief, the results suggest that the T/T genotype of the BsmI (rs1544410) VDR polymorphism and the G/G genotype of the Taq1 (rs731236) VDR polymorphism figured more prominently among the myocardial infarction CAD patients." (PMID 33863283, 2021). "A recent study showed that VDR variant (rs7968585) can predict risk for hip fracture, cancer, myocardial infarction, and mortality among older Caucasian individuals with a low vitamin D status." (PMID 27595605, 2016). "Therefore, we expanded our research conducted on VDBP polymorphisms in a CAD cohort with myocardial infarction to the analysis of the Fok1 (rs2228570), BsmI (rs1544410) and Taq1 (rs731236) VDR polymorphisms as well." (PMID 33863283, 2021). "The results show an association between the T/T genotype of the BsmI (rs1544410) and the G/G genotype of the Taq1 (rs731236) VDR polymorphism and CAD patients after acute myocardial infarction." (PMID 33863283, 2021). "Our study provides evidence for association between the T/T genotype of the BsmI (rs1544410) and the G/G genotype of the Taq1 (rs731236) VDR polymorphism and CAD patients after acute myocardial infarction." (PMID 33863283, 2021). "In previous studies, the VDR/RXR canonical pathway (vitamin D receptor/retinoid X receptor) has been associated with cardiac arrhythmia and myocardial infarction." (PMID 32189431, 2020). "Therefore, the objective of this study was to analyze three well-studied VDR gene polymorphisms—Fok1 (rs2228570), BsmI (rs1544410) and Taq1 (rs731236)—in a cohort of CAD patients after acute myocardial infarction." (PMID 33863283, 2021). "A recent study indicates that VDR polymorphisms may interact with circulating levels of vitamin D (25(OH)D) in determining major clinical outcomes, including a composite outcome of incident hip fracture, myocardial infarction (MI), cancer, and mortality." (PMID 24557774, 2014). "Our data suggest that the lack of vitamin D signalling in normocalcaemic vitamin D receptor mutants has no major detrimental effect on cardiac function and outcome post-myocardial infarction." (PMID 30273386, 2018). "Surprisingly, survival rate, cardiac function as measured by echocardiography and intra-cardiac catheterisation and cardiomyocyte size were indistinguishable between normocalcaemic vitamin D receptor mutant mice and wild-type controls, 2 and 8 weeks post-myocardial infarction." (PMID 30273386, 2018).
urolithiasis (17 papers, 2013 to 2023). Stone(s) within the urinary tract. "Several studies analyzed the associations of VDR gene expression with urolithiasis risk in different ethnic groups." (PMID 35546405, 2022). "The results demonstrated that the VDR gene TaqI TT genotype was related to decreased risk of urolithiasis in the overall population (TT vs. Tt+tt: P = 0.011, OR = 0.824, 95% CI = 0.709-0.957)." (PMID 32346382, 2020). "A series of studies investigated the association between these polymorphisms of VDR gene and the risk of urolithiasis, but the findings have been conflicting." (PMID 32650740, 2020). "According that, the findings indicated that none of the expected heterogeneity parameter were the source of heterogeneity for the association between VDR gene polymorphism and the risk of urolithiasis." (PMID 32650740, 2020). "To assess correlations between VDR gene variants ApaI (rs7975232), BsmI (rs1544410), FokI (rs2228570), and TaqI (rs731236) and urolithiasis susceptibility, we performed the present study through meta-analysis." (PMID 32346382, 2020). "Several investigations have noted that VDR gene SNPs have been contributing genetic factors in susceptibility to urolithiasis." (PMID 32650740, 2020). "As a result, we performed a meta-analysis to investigate the consequence of the common four SNPs in the VDR gene, namely FokI (rs2228570), TaqI (rs731236), BsmI (rs1544410), and ApaI (rs7975232) on the risk of urolithiasis." (PMID 32650740, 2020). "The relationship between urolithiasis and vitamin D receptor (VDR) gene variants is still under debate according to the available published literature." (PMID 32346382, 2020). "The subgroup analyses were conducted based on the ethnicity to identify the potential impression of the genetic background on the association of VDR gene polymorphisms and urolithiasis." (PMID 32650740, 2020). "In the current most recent meta-analysis, 33 case-control association studies evaluating the VDR gene SNPs and urolithiasis risk were analyzed." (PMID 32650740, 2020). "Herein, a meta-analysis was carried out to attain a conclusive estimate of the association between VDR gene single nucleotide polymorphisms (SNPs) and urolithiasis risk." (PMID 32650740, 2020). "On the other hand, a meta-analysis in 2014 with respect to the study of the associations between VDR gene SNPs and urolithiasis risk included 20 studies in the analysis." (PMID 32650740, 2020). "Literature search led to finally finding of 33 studies evaluating the VDR gene SNPs and urolithiasis risk." (PMID 32650740, 2020). "Data from GWASs as well as association studies in different ethnic groups have revealed that VDR gene polymorphisms play a role in altering the risk of urolithiasis development." (PMID 32650740, 2020). "Association between VDR gene polymorphisms, including FokI (rs2228570), TaqI (rs731236), BsmI (rs1544410), and ApaI (rs7975232), and urolithiasis risk was evaluated using pooled odds ratio (OR) and their corresponding 95% confidence interval (CI)." (PMID 32650740, 2020). "Nevertheless, some biochemical metabolic parameters such as CO2CP, uric acid, serum Na level, and a VDR gene loci (FokI) are associated with urolithiasis in children." (PMID 30742686, 2019). "Some researchers evaluated the association of VDR gene polymorphisms with metabolic disturbances in children with urinary stones." (PMID 30742686, 2019). "Here we determined biochemical metabolic levels and VDR FokI polymorphisms in Uyghur children with urolithiasis in China, and evaluated the associations of biochemical metabolic levels with FokI genotypes." (PMID 30742686, 2019). "In this study, we measured biochemical metabolic levels and VDR FokI polymorphisms in Uyghur children with urolithiasis in China, and evaluated the associations of biochemical metabolic levels with FokI genotypes." (PMID 30742686, 2019). "A recent meta-analysis displayed a significant contribution of vitamin D receptor polymorphisms to urolithiasis risk." (PMID 28335477, 2017).